GZF1 (GDNF inducible zinc finger protein 1)
Description:
Transcriptional repressor that binds the GZF1 responsive element (GRE) (consensus: 5'-TGCGCN[TG][CA]TATA-3'). May be regulating VSX2/HOX10 expression.
Synonyms: ZBTB23; ZNF336; dJ322G13.2; JLSM
Tractability: No criterion of Open Targets' tractability assessment is met for any kind of drug.
Gene: Protein-coding gene on chromosome 20 (23,362,000 to 23,373,062, forward strand). Ensembl gene ENSG00000125812.
Subcellular location: Cytoplasm; Nucleus, nucleoplasm; Nucleus, nucleolus
Subcellular location (Human Protein Atlas): Nucleoli; Nucleoplasm
Gene Ontology:
Molecular function: DNA-binding transcription repressor activity, RNA polymerase II-specific; RNA polymerase II cis-regulatory region sequence-specific DNA binding; sequence-specific DNA binding; DNA-binding transcription factor activity, RNA polymerase II-specific
Biological process: negative regulation of DNA-templated transcription; negative regulation of transcription by RNA polymerase II; regulation of DNA-templated transcription
Cellular component: cytoplasm; nucleolus; nucleoplasm; nucleus
Genetic constraint (gnomAD): Loss-of-function variants: 32 observed, 49.38 expected, observed/expected ratio (o/e) 0.65, 90% interval 0.49 to 0.87. The upper end of that interval is the gene's LOEUF score, 0.87, which puts it in group 3 of 6, group 1 being the genes least tolerant of losing a copy. Missense variants: 776 observed, 904.21 expected, observed/expected ratio (o/e) 0.86, 90% interval 0.81 to 0.91. Synonymous variants: 359 observed, 356.82 expected, observed/expected ratio (o/e) 1.01, 90% interval 0.92 to 1.1.
Homologues: Orthologues: chimpanzee GZF1 (99% identical), macaque GZF1 (98% identical), dog GZF1 (85% identical), rat Gzf1 (82% identical), mouse Gzf1 (82% identical), guinea pig GZF1 (79% identical), pig GZF1 (68% identical), tropical clawed frog gzf1 (59% identical). Paralogues in human: ZNF34 (20% identical), ZNF407 (20% identical), ZNF214 (19% identical), ZNF287 (19% identical), ZNF416 (19% identical), ZNF527 (19% identical), ZKSCAN7 (19% identical), ZNF285 (19% identical), ZNF333 (19% identical), ZNF530 (19% identical), ZNF776 (18% identical), ZNF17 (18% identical), and 38 more.
Diseases named in the same sentence as GZF1 in open-access papers:
GZF1 is named in the same sentence as 7 diseases in open-access papers, as found by Europe PMC text mining. Sharing a sentence is not in itself a finding about the gene and the disease. The quoted sentences say what the papers report.
autism (1 paper, 2024). Persistent deficits in social interaction and communication and interaction as well as a markedly restricted repertoire of activity and interest as well as repetitive patterns of behavior. "The WES approach allowed us to identify five clinically relevant variants in the GZF1, NFIX, TRRAP, FGFR2 and PAX2 genes associated with Larsen, Malan, developmental delay with or without dysmorphic facies and autism, LADD1 and papillorenal syndromes." (PMID 38909058, 2024).
Larsen syndrome (1 paper, 2024). A rare skeletal dysplasia characterized by congenital dislocation of large joints, foot deformities, cervical spine dysplasia, scoliosis, spatula-shaped distal phalanges and distinctive craniofacial abnormalities, including cleft palate. "It is noteworthy that this represents the third report linking GZF1 mutations to AR Larsen syndrome, with the first documented patient in the Mexican population." (PMID 38909058, 2024).
Malan syndrome (1 paper, 2024). "The other two frameshift GZF1 p.[His407Profs*61] and NFIX p.[Pro249Metfs36] pathogenic variants causing JLSM (Patient 1) and Malan syndrome (Patient 2) are novel genotypes." (PMID 38909058, 2024).
myopia (1 paper, 2022). "High myopia is near-universal, and sensorineural hearing loss is very common in patients with variants in genes for type IX or XI collagen, although hearing appears spared in the LRP2 and LOXL3 patients and is variable in GZF1." (PMID 35885918, 2022).
skeletal dysplasia (1 paper, 2024). Any Mendelian diseases that affects growth and development of the skeleton. "However, the proband’s sister showed a skeletal dysplasia phenotype, which could be the result of other GZF1 pathogenic mechanisms that are still unknown." (PMID 38909058, 2024).
GZF1 also shares sentences with these, for which no sentence is quoted: developmental delay (1 paper); papillorenal syndromes (1).